CD274 (CD274 molecule)
Diseases named in the same sentence as CD274 in open-access papers (continued):
Sharing a sentence is not in itself a finding about the gene and the disease.
tumor (continued). "Here, we show that sPD-L1 in human healthy tissues and tumours is produced by exaptation of an intronic LINE-2A (L2A) endogenous retroelement in the CD274 gene, encoding PD-L1, which causes omission of the transmembrane domain and the regulatory sequence in the canonical 3’ untranslated region." (PMID 31729316, 2019). "(A) CD274 variant 1 and CD274-L2A expression across TCGA tumour and GTEx healthy samples." (PMID 31729316, 2019). "We thus examined tumor-associated Treg for expression of the immunosuppressive surface molecule programmed death-ligand 1 (PD-L1, also known as CD274), which binds to its receptor, programmed death-1 (PD-1), on T cells and confers an inhibitory signal repressing T cell immunity." (PMID 30651930, 2018). "Notably, PDL1, encoded by the CD274 gene, is a major driver of tumor immune escape, and its changes in expression have garnered significant attention, particularly during the “cold‐to‐hot” transformation of tumor immune phenotypes, where its expression levels increase." (PMID 39976106, 2025). "However, the direct association between CD274 expression and prognosis needs to be further verified, as it may be regulated by molecular characteristics such as tumor mutation load (TMB) or microsatellite instability (MSI)." (PMID 40568599, 2025). "In many of these neoplasms, elevated PD-L1 expression is thought to be associated with the repression of miR-197, suggesting that the blockade of a transcriptional regulatory mechanism plays a part in the induction of PD-L1-encoding CD274 in certain transformed cells." (PMID 38920700, 2024). "Hence, the pre-existing anticancer activities of patients with high risk scores may be restrained by the higher level of tumour infiltrated macrophages (M2) and the over-expression of many inhibitory immune checkpoints (such as CD274 and LAG3)." (PMID 34975891, 2021). "However, in recent studies PD-L1/CD274 expression by tumor tissues was associated with the presence of tumor-infiltrating lymphocytes, which could be involved in better immunotherapy-triggered prognosis." (PMID 33066260, 2020). "Programmed death ligand-1 (PD-L1), encoded by the CD274 gene, is a pivotal checkpoint that plays a central role in immune regulation and tumor immune evasion." (PMID 41486149, 2026). "After intravenous injection into HNSCC-bearing mice, ARPC can induce heat stress upon NIR-II laser irradiation at tumor sites, causing the upregulation of Hsp70 to trigger CRISPR/Cas9 for CD274 editing." (PMID 41624538, 2026). "In vitro assays confirmed that endothelial cells were educated by SLC1A3hi tumor cells that undergo malignant transition, drastically upregulating immune-suppressive factors, including CD274, TGFB1, IL10, and IDO1." (PMID 42112375, 2026). "In an extended cohort of 70 CSLs (tumor, matched normals, and controls), a recurrent C > T single-nucleotide variant in exon 4 of CD274/PD-L1 was identified in 54 of 68 (79.4%) CSLs with diagnosed UGC." (PMID 41751606, 2026). "These distinct enrichment profiles underscore the divergent functional landscapes of these genes: PSD3 appears to drive tumor-intrinsic processes, while CD274 and TNFSF18 modulate tumor-immune interactions." (PMID 40895529, 2025). "Integrating CD274 (PD‐L1) expression enhanced prognostic stratification, with patients demonstrating low expression of the HLA‐DR+ tumor cell signature and low CD274 enjoying the most favorable survival outcomes (p = 0.028)." (PMID 40464412, 2025). "A high level of p130Cas expression in circulating tumor cells was correlated with the expression of CD274 and the occurrence of EMT." (PMID 40362257, 2025). "CD274, also known as programmed death-ligand 1 (PD-L1), binds to the PD-1 receptor on T cells, inhibiting their effector functions and allowing tumor cells to evade immune surveillance." (PMID 39858472, 2025).
tumor (continued). "The genes with low expression of CD274 and low expression in tumor patients were enriched in Neuroactive ligand-receptor interaction, Hormone signaling and cAMP signaling pathway." (PMID 40568599, 2025). "CD274 was significantly upregulated in neoplasms compared to NOM groups, especially in HNSCC groups (log2 fold > 0.25 and p < 0.05)." (PMID 40392349, 2025). "Senescent cells tend to accumulate in the TME and evade immune surveillance by upregulating CD274, thereby promoting tumor progression." (PMID 40642086, 2025). "In contrast, Texh_CD4, Treg, and Tactivated_CD4 cells exhibited higher levels of PD-1 expression, while HGSOC tumor cells displayed low PD-L1 (or CD274) expression level." (PMID 40260248, 2025). "PDL1 (CD274) - PD1 and TIGIT - CD155 (PVR) are common immune checkpoint pathways in tumors, through which tumor cells can inhibit the function of T cells by expressing CD274 and PVR." (PMID 40110547, 2025). "Some reported cases showed focal amplification of PD-L1 (CD274) at 9p24.1, acting in synergy with constitutive pSTAT3 signaling, which favors the tumor’s immune escape." (PMID 40565334, 2025). "This phenotype was reversed at a later timepoint which coincided with downregulation of immunosuppressive Cd274+Lcn2+ neutrophils and upregulation of anti-tumor P2rx1+Nrf2− neutrophils." (PMID 40568084, 2025). "Collectively, these data underscore the importance of tumor‐specific HLA‐DR expression, particularly in conjunction with CD274 status, as a robust prognostic biomarker in HCC." (PMID 40464412, 2025). "Intriguingly, the results indicated that the checkpoint gene expression levels of CD274 and PDCD1, which can encode PD-L1 and PD-1 protein inducing the suppression of anti-tumor immunity, were higher in high-risk patients than in low-2risk patients." (PMID 40761262, 2025). "The co-expression of CDKN2A and the immune checkpoint gene CD274 was enhanced with elevated tumor purity." (PMID 41341386, 2025). "PD-L1 [also known as cluster of different (CD274) or B7 homology 1 (B7-H1)], expressed on APCs, macrophages, and tumor cells bind PD-1 on T cells, recruiting SHP-1 and SHP-2 phosphatases." (PMID 40927720, 2025). "Concurrently, Mg2+ influx reshapes the immune microenvironment: it downregulates immunosuppressive molecules (e.g., CD274/PD-L1) and upregulates resting memory T cell infiltration, while inhibiting pro-tumor immune subsets." (PMID 41562086, 2025). "CD274 is a well-established immune checkpoint molecule that plays a pivotal role in immune escape mechanisms by inhibiting T cell activity in the tumor microenvironment." (PMID 40895529, 2025). "The PD-1, encoded by the PDCD1 gene, is expressed on activated T-cells, while its ligands, PD-L1 and PD-L2, encoded by CD274 and CD273, are expressed in both immune and tumor cells." (PMID 40806346, 2025). "The association between PIEZO1 and tumor microenvironment scores (Stromal, Immune, ESTIMATE) or immune checkpoint markers (CD274, CTLA4, LAG3, PDCD1, PDCD1LG2) were analyzed using the R language." (PMID 40977743, 2025). "Among these genes were STAT1, a central regulator of immune responses, and PD-L1 (CD274), a key immune checkpoint molecule with a fundamental role in anti-tumor immunity." (PMID 40777467, 2025). "In tumor cells, CD274 interacts with CD279 on T cells, leading to phosphorylation of immunoreceptor tyrosine motifs, suppression of T cell signaling, and subsequent immune evasion." (PMID 41409271, 2025). "Fourth, PIEZO1 shows positive associations with tumor microenvironment scores (Stromal/Immune/ESTIMATE) and immune checkpoint markers (CD274, CTLA4, LAG3, PDCD1, PDCD1LG2)." (PMID 40977743, 2025). "At the same time, MUC1 is involved in regulating the tumor microenvironment by modulating the expression of CD274/PD-L1." (PMID 40655139, 2025).
tumor (continued). "CD274 is well-established as an immune checkpoint molecule that enables tumor immune evasion by binding to PD-1 on T cells, thus suppressing their cytotoxic function." (PMID 40895529, 2025). "Programmed death ligand 1 (PD-L1) (Cd274) on tumor surface enables the evasion of immune cells and suppression of T cells." (PMID 40055805, 2025). "It has been reported that IL-6 and IL-1β can stimulate tumor cells to express CD274 (PD-L1) proteins via activating the STAT3 signaling pathway, thereby facilitating tumor cell immune escape." (PMID 39911394, 2025). "PD-L1, which is also referred to as CD274 or B7-H1, is commonly expressed on the surface of various tumor cells." (PMID 40804393, 2025). "The tumor samples were divided into CD274-high and CD274-low expression samples and 873 genes were up-regulated and 1,010 genes were down regulated between CD274-high and CD274-low samples." (PMID 40568599, 2025). "In TNBC, CXCL8 derived from tumor-associated adipocytes regulates the immunosuppressive microenvironment and promotes tumor progression by up-regulating the expression of CD274 and inhibiting T cell infiltration." (PMID 40256431, 2025). "Interrogation of TCGA datasets revealed concurrent upregulation of CRTC1 and PD-L1 (CD274) in NSCLC tumor specimens." (PMID 40977688, 2025). "Its primary ligand, programmed death-ligand 1 (PD-L1) (CD274), is a type I transmembrane protein widely expressed on tumor cells and tumor-infiltrating immune cells." (PMID 41281945, 2025). "Further demonstrated in this same TNBC model, dual hairpin targeting of UBR5 and PD-L1 (CD274) resulted in dramatically reduced tumor growth and lung metastasis and significantly extended survival." (PMID 39857943, 2025). "Programmed death-ligand 1, also known as PD-L1 (CD274), is a transmembrane protein primarily expressed in various tumor cells, tumor-infiltrating cells, and antigen-presenting cells (APCs)." (PMID 39860407, 2025). "In addition, CD274 genes associated with high expression are enriched in Necroptosis and Cell adhesion molecules, suggesting that CD274 may influence anti-tumor immune responses by regulating tumor cell death patterns (such as immunogenic death) or cell to cell interactions." (PMID 40568599, 2025). "CD274 (PD‐L1), primarily expressed by plasmacytoid DCs, showed tumor/stroma overexpression in only a minor subset of stRNA‐seq samples." (PMID 41057994, 2025). "GSEA analysis showed that the genes with high expression of CD274 and high expression in tumor patients were enriched in Necroptosis, JAK-STAT signaling pathway and Cell adhesion molecules." (PMID 40568599, 2025). "Significant correlations were observed, with Spearman coefficients ranging from 0.031 to 0.526 (all p < 0.05), supporting the notion that MSL1 and MSL3 cooperatively regulate CD274 expression and contribute to tumor immune escape." (PMID 41409271, 2025). "Key genes such as CD276, CD70, and CD274, known for their roles in immune modulation and tumor microenvironment influence, were notably divergent." (PMID 40299331, 2025). "Given the immunomodulatory roles of CD274 and TNFSF18, along with the emerging relevance of PSD3 in cancer biology, we next investigated their associations with tumor-infiltrating immune cells using immune deconvolution data from the GEO dataset GEO dataset." (PMID 40895529, 2025). "CD274/PD-L1 is expressed in many types of tumors and inhibits T cell activity through interaction with its receptor, PD-1, thereby helping tumor cells evade host immune surveillance." (PMID 40103813, 2025). "CD274 encodes programmed death-ligand 1 (PD-L1), the principal ligand for PD-1, which is widely expressed in both tumor and immune cells and inhibits T cell activity via the PD-1/PD-L1 interaction." (PMID 40507905, 2025).
tumor (continued). "Gao’s team conducted comprehensive studies using CD274 knock-off tumor cells for chromatin immunoprecipitation and sequencing (ChIP-seq), revealing that nuclear PD-L1 specifically triggers gene expression in immune response pathways." (PMID 40573881, 2025). "Patients harboring elevated proportions of HLA‐DR+ tumor cells (HR = 2.24, 95% CI: 1.15–4.35, p = 0.006) or HLA‐DR+CD274+ tumor cells (HR = 2.76, 95% CI: 1.32–5.78, p < 0.001) had significantly worse OS." (PMID 40464412, 2025). "Researchers found that CAF autophagy upregulates the expression of USP14 in PDAC tumor cells through IL‐6, thereby promoting elevated levels of CD274/PD‐L1 and inducing immunotherapy resistance in PDAC." (PMID 41164803, 2025). "Together, these findings suggest a previously unrecognized association between MSL1 and CD274 (PD-L1), highlighting a potential epigenetic link between the MSL complex and tumor immune regulation." (PMID 41409271, 2025). "This complex binds to the promoter region of CD274, inhibiting PD-L1 expression and thereby enhancing anti-tumor immune responses in T cells in vivo." (PMID 40006729, 2025). "In both HGSOC with HRD phenotype and BRCA1 mutant TNBC, CD274 (PD-L1) expression on tumor cells is also upregulated." (PMID 40830526, 2025). "The expression of CD274 on tumor cells and immune cells can inhibit T-cell activation, thereby suppressing antitumor immune responses." (PMID 40561678, 2025). "Previous studies have established that the expression of CD274/PD-L1 was associated with multiple signaling pathways, including IL-6/JAK/STAT3, PI-3K/AKT/mTOR, JAK/STAT, and WNT, which collectively influenced the tumor immune microenvironment." (PMID 40953006, 2025). "scRNA-seq also revealed the downregulation of Ptgs2 in the predominant tumor cluster 0 and an overall decrease in the immunosuppressive Cd274+ Lcn2+ Ptgs2+ neutrophil cluster 0 in the CAR-T-treated group." (PMID 40568084, 2025). "Although there are many studies on the role of CD274 in tumor immunity, for example, the expression of CD274 can inhibit anti-tumor immunity, especially by interacting with the PD-1 receptor on T cells, thereby reducing the activity and efficacy of T cells." (PMID 40642086, 2025). "Of note, a heatmap based on GSEA showed several tumor-associated immune checkpoints, such as H2-Ab1, CD86, CD80, and CD276, CD274 (Pdl1), were downregulated upon Prmt3 deletion." (PMID 40050608, 2025). "To address alternative sources of CD80 and CD86 in the tumor environment, we profiled expression of these markers along with PDL1 (CD274) in published scRNASeq data from five different murine tumors including MC38." (PMID 41417245, 2025). "The interaction between CD279 on tumor-infiltrating lymphocytes and CD274 or CD273 (PD-L2) on tumor cells constitutes a major mechanism of immune evasion." (PMID 41409271, 2025). "We then found from GEPIA database that PRC1 had a positive expression correlation with ICD markers (CRT and HMGB1) and the immune checkpoint gene CD274 in tumor tissues from COAD and READ patients." (PMID 40847353, 2025). "Acidovorax temperans has been shown to skew neutrophil maturation toward a protumor phenotype, characterized by upregulation of markers associated with excessive infiltration (Icam), immunosuppression (Cd274/PD-L1), and tumor promotion (Siglecf)." (PMID 41516132, 2025). "Microsatellite instability (MSI), tumor mutational burden (TMB), and CD274 (PD-L1) expression are recognized as emerging markers for evaluating the efficacy of ICI therapies." (PMID 40406134, 2025). "PD-L1 (also known as CD274 or B7-H1) is a membrane receptor molecule expressed on tumor cells and target cells." (PMID 41369006, 2025). "Programmed death ligand 1 (PD-L1, also known as B7-H1 or CD274) in combination with programmed cell death-1 (PD-1) plays a relevant role in tumor escape of immune surveillance." (PMID 40149335, 2025).
tumor (continued). "To further assess the clinical relevance of HuR in tumor diagnosis, we conducted a pan-cancer analysis comparing the correlation between HuR and PD-L1 (CD274) expressions in both normal and tumor samples." (PMID 40853971, 2025). "CD274, a protein important for immune regulation, is chiefly located on the surface of antigen-presenting cells, tumor cells, and different cell types." (PMID 40642086, 2025). "LGALS3 expression showed a significant positive association with CD274, TIGIT, PDCD1, HAVCR2, CTLA4, LAG3, as well as PDCD1LG2 after adjustment for tumor purity in HCC." (PMID 38643145, 2024). "The result showed that the genes (including CD276, CD274, and PDCD1LG2) had functions on T-cell co-inhibition contributing to tumor cell evasion were enriched in high-risk groups and become important targets for blockade-based immunotherapy in cancer;." (PMID 38665430, 2024). "Hypoxia, induced by HIF-1α, triggers PDL-1 (CD274) expression in tumor and immune cells, thus promoting immune suppression in the TIME." (PMID 39119332, 2024). "Tumour immunogenicity is a contemporary challenge in oncology, with CD274 serving as a focal point for innovative immunotherapeutic strategies." (PMID 38802631, 2024). "The slight increase observed in PDL1 gene expression (CD274) analyzed by Nanostring reflects its expression at the microenvironment, but also in tumor cells, another limit of this specific approach." (PMID 38280007, 2024). "Extensive research has demonstrated that CD274 (PD-L1) is prominently overexpressed on the surface of malignant tumour cells." (PMID 38802631, 2024). "The interaction between overexpressed PD1 (also known as CD279) on tumour infiltrating lymphocytes (TILs) due to overstimulation and PD-L1 (also known as CD274 or B7-H1) expressed on tumour cells leads to inactivation of the TILs." (PMID 39416707, 2024). "CD274 is identified as an adhesion molecule present on T-cells, antigen-presenting cells and tumor cells according to KEGG pathways (map04514 and map05235)." (PMID 38658744, 2024). "CXCL8 modulates the TNBC immune microenvironment by controlling the infiltration of CD4+ and CD8+ T cells and increasing CD274 (PD-L1) expression, unveiling potential therapeutic targets for anti-tumor immunotherapy." (PMID 38791448, 2024). "PD-1 and its ligands PD-L1 (CD274) or PD-L2 (CD273) play a key role in the immune escape of tumor cells, which can significantly inhibit the function of T cells, while tumors can resist the attack of the immune system through high expression of PD-L1/PD-L2." (PMID 39003253, 2024). "Among these factors, chemokine CXCL11 caught our particular interest, because it has recently been shown, that CXCL11 is involved in tumor lymphatic cross talk and the regulation of checkpoint molecule PD-L1 (CD274) in cancer tissues." (PMID 38609887, 2024). "CD274 is predominantly expressed by tumor cells, binding with programmed cell death-1(PD-1) on the surface of T cells and triggering immune escape." (PMID 38233752, 2024). "scRNA-seq of Kaede-red CD45+ cells in tumour-dLNs (integrated with CD45+ cells from control LNs) included a prominent Ccr7+Cd274+Pdcd1lg2+ DC cluster among myeloid cells." (PMID 38267413, 2024). "Differential expression of colorectal neoplasia expressed (CRNDE) is positively correlated with tumor immunity, as it can increase the expression of immune checkpoints such as CD274 (PDL1), PDCD1LG2 (PD-L2), CD86, and CD276." (PMID 38967893, 2024). "The combination of PDCD1 (PD‐1) and CD274 (PD‐L1) can disrupt the immune environment, culminating in immune evasion by tumour cells, and these molecules can be targeted for therapeutic intervention using immune checkpoint inhibitors." (PMID 38429900, 2024). "Cytokines and signalling molecules have been used by cancer cells to regulate the immune system in their favour, for example tumours can express CD274 in order to directly supress T-cell activity." (PMID 38773187, 2024).